DNMT1 (DNA methyltransferase 1)
Diseases named in the same sentence as DNMT1 in open-access papers (continued):
Sharing a sentence is not in itself a finding about the gene and the disease.
colorectal cancer (continued). "Recently, it has been shown that apple polyphenols has potent DNA demethylation activity in colorectal cancers by reducing DNMT1 expression with a subsequent activation of TSGs such as hMLH1, p14ARF and p16INK4A." (PMID 21496237, 2011). "Since our data indicated a strong link between DNA methylation and the H3K36me3 mark, we investigated epigenetic profiles in the HCT116 colorectal cancer cell line and in its isogenic counterpart with double knockout of DNMT1 and DNMT3B." (PMID 21526191, 2011). "A phase I pilot study showed that chronic intake of black raspberries by patients suffering from colorectal cancers leads to down-regulation of DNMT1 and re-expression of TSGs through a DNA demethylating process." (PMID 21496237, 2011). "We next analyzed methylation of each gene in a colorectal cancer cell line (HCT116) after partial knockout of DNMT1, knockout of DNMT3b or knockout of both enzymes (DKO)." (PMID 17967063, 2007). "This is consistent with what is observed in human colorectal carcinoma cells, which appear to require both DNMT1 and DNMT3b expression to retain p16 silencing via promoter region hypermethylation." (PMID 17938735, 2007). "We recently generated degron alleles of DNMT1 and UHRF1 in colorectal cancer cells." (PMID 40595593, 2025). "The study demonstrated that DNMT1 deletion in colorectal cancer cells led to an upregulation of TET2 expression, re-expression of tumour suppressor proteins (p16ink4A and p15ink4B), CDKN2A promoter demethylation, and associated resistance to DNMTi in DNMT1-deleted cells." (PMID 40011240, 2025). "Moreover, in colorectal cancer cell lines, kaempferol can bind DNMT1 and downregulate the methylation of tumor suppressor gene DACT2, thus inhibiting the Wnt/β-catenin pathway." (PMID 39858410, 2024). "Also, the administration of GTE capsules (800 mg EGCG) seems to regulate biomarkers related to colorectal cancer pathogenesis, especially genes associated with selenoproteins, WNT signaling (β-catenin), inflammation (NF-κB), and methylation (DNMT1)." (PMID 37446908, 2023). "Interestingly, the depletion of HAUSP in both human embryonic kidney cells and colorectal cancer cells resulted in an increase in DNMT1 ubiquitination and a reduction in DNMT1 protein expression." (PMID 35052383, 2021). "Laccaic acid could produce epigenetic modifications in colorectal cancer, primarily downregulating DNMT1 and HDAC1 expression." (PMID 34835969, 2021). "In HCT116, HT29, and YB5 colorectal cancer cell lines, kaempferol was found to bind to DNMT1, and it significantly downregulated DACT2 methylation, upregulated expression of this tumor suppressor gene, blocked the Wnt/β-catenin signaling pathway, and inhibited tumor cell proliferation and migration." (PMID 34235089, 2021). "In addition, the combinatorial treatment of PEITC with laccaic acid (LA) showed synergistic antitumor activity on colorectal cancer cells with noticeable ability to down-regulate the expression of DNMT1 and HDAC1." (PMID 34835969, 2021). "To do this, we first used a well-established model, the paired colorectal cancer lines HCT116 and its derivative HCT116 DKO (double knockout), which carries mutations in two of the methyltransferase genes DNMT1 and DNMT3B and is known to be hypomethylated at many loci." (PMID 30777123, 2019). "Similarly, another study identified LSD1 as a component of β-catenin complexes that also contained DNMT1 in human colorectal cancer cell line HCT11648." (PMID 30894540, 2019). "Additionally, BNIP3 upregulation in a DNA demethylation-dependent manner in colorectal cancer has been reported to overcome apoptosis resistance after verticillin A treatment and related to DNMT1 inhibition following radiotherapy and chemotherapy." (PMID 31835431, 2019). "Furthermore, we are able to show immunoprecipitation between Lsh and Dnmt1 in SW620 colorectal cancer cells indicating the proteins are partners in vivo." (PMID 26491684, 2015).
colorectal cancer (continued). "Indeed, it has been shown that apple polyphenols has potent DNA demethylation activity in colorectal cancers by reducing DNMT1 expression with a subsequent activation of TSGs such as p16INK4A." (PMID 23688286, 2013). "Using luteolin to target calpain, UHRF1, and DNMT1 may help prevent or treat colorectal cancer." (PMID 35327559, 2022). "We generated colorectal cancer cell lines in which the endogenous copies of UHRF1 and/or DNMT1 are tagged with fluorescent markers as well as degron tags, allowing for their rapid and controlled depletion." (PMID 38580649, 2024). "Using a specific LSD1 inhibitor, CBB3001, it was found that in human colorectal carcinoma HCT116 cells, inhibition of LSD1 was sufficient to induce the proteolytic degradation of DNMT1." (PMID 38396925, 2024). "In colorectal cancer, the knockdown of LINC00337 inhibited angiogenesis and proliferation of CRC cells because LINC00337 inhibited CNN1 expression by recruiting DNMT1." (PMID 37781524, 2023). "Aza-T-dCyd, decitabine and azacitidine all inhibited the expression of DNMT1 and cell growth, and induced apoptosis and/or cytotoxicity in HCT116 DNMT1+/+ colorectal cancer cells." (PMID 37045940, 2023). "The administration of GTE capsules containing 800 mg of EGCG seems to regulate biomarkers related to colorectal cancer pathogenesis, including selenoproteins, WNT signaling (β-catenin), inflammation (NF-κB), and methylation (DNMT1)." (PMID 37446908, 2023). "To generate such a model, we treated two colorectal cancer cell lines with increasing concentrations of GSK5032, a DNMT1 specific inhibitor, over several months." (PMID 35654826, 2022). "Analysis of additional colorectal cancer cell lines, DLD1, HT29, and RKO, after DNMT1 knockdown with higher and lower shRNA efficiencies confirmed DNMT1-dependent repression of the LY6G6D transcript." (PMID 35953834, 2022). "A similar increase in DNMT1 ubiquitination levels and a decrease in its protein expression were reported when HAUSP was knocked out in colorectal cancer cells." (PMID 35052383, 2021). "To explore the mechanism of how LKB1 promoter methylation is elevated, we characterized the expression of three DNMTs, i.e. DNMT1, 3a and 3b, in normal colon mucosa, PJS polyps and colorectal cancer in PJS patients." (PMID 32799895, 2020). "Similar to DNMT1, DNMT3a also have strong staining in the epithelial cells of PJS polyps and colorectal cancer in PJS patients compared to the normal samples." (PMID 32799895, 2020). "DNMT1 is weakly expressed in normal mucosa, while its expression has elevated in the epithelial cells of PJS polyps and colorectal cancer in PJS patients." (PMID 32799895, 2020). "We next tested if 2i also regulates UHRF1 and DNMT1 in HCT116, a human colorectal carcinoma cell line." (PMID 30696879, 2019). "To further confirm the functional impact of DNA methylation alterations on gene expression, we utilized two human colorectal carcinoma cell lines, namely HCT116 wild type and HCT116 DNMT1/DNMT3B double knockout (DKO) cells." (PMID 30911103, 2019). "In colorectal cancer (CRC) tissues and cell lines, miR-342 functioned as a tumor suppressor gene in CRC development by targeting DNA methyltransferase 1 (DNMT1) and aberrant DNA hypermethylation." (PMID 28890884, 2017). "Both Dnmt1 and Dnmt3b interact with the polycomb group repression complexes (PRC1 and PRC2), and regulate distinct sites in colorectal cancer development." (PMID 26808831, 2016). "In addition, colorectal carcinoma (CRC) cells which were subjected to hypoxia and hypoglycemia had reduced DNMT1, DNMT3a, and DNMT3b mRNAs, resulting in a decrease in the 5mC level at the proximal promoter region of p16INK4a." (PMID 26861406, 2016).
colorectal cancer (continued). "To observe the consequences of PADI4-mediated DNMT3A upregulation specifically, we used the colorectal cancer cell line HCT-116, where both the DNMT1 and DNMT3B DNMTs have been genetically disrupted (DKO cells) and where DNMT activity is minimal." (PMID 24957603, 2014). "While the loss of LSD1 caused increased levels of H3K4me1/me2, the inactivation of LSD1 in mouse ESCs, human teratocarcinoma PA1 cells, human colorectal carcinoma HCT116, and lung carcinoma H1299 cells led to the proteolytic downregulation of the methylated DNMT1, SOX2, and E2F1 proteins." (PMID 38396925, 2024). "Furthermore, in colorectal cancer, miR-152-3p was found to upregulate and inhibit TMSB10, while upregulation of DNMT1 can reverse the effect of miR-152-3p on CRC tumor growth." (PMID 37781524, 2023). "This may extend to DNA methylation as well, since inhibition of DNA methyltransferase 1 and 3 (DNMT1 and DNMT3) improves infectivity of HCMV in human HCT116 colorectal carcinoma cells." (PMID 37439556, 2023). "Furthermore, DNMT1 maintained the methylation of miR-152-3p to regulate TMSB10 expression, thereby affecting the biological characteristics of colorectal cancer cells." (PMID 36276278, 2022). "We treated two colorectal cancer cell lines from a male (HCT116) and a female (RKO) with increasing doses of a DNA methyltransferase 1 (DNMT1)-specific inhibitor (GSK3685032/GSK5032) over several months to remove as much non-essential CpG methylation as possible." (PMID 35654826, 2022). "Moreover, MIR210HG was identified as prognostic marker of colorectal cancer and shown to promote the proliferation and invasion of non-small-cell lung carcinoma via inhibiting the expression of CACNA2D2 by recruiting DNMT1." (PMID 33375322, 2020). "In colorectal cancer, NUSAP1 is an independent prognostic biomarker and its depletion induced cell apoptosis, and inhibited cell migration, cell invasion, cell proliferation, and EMT by inhibiting the expression of DNA methyltransferase 1 (DNMT1)." (PMID 30678687, 2019). "Overexpression of DNMT1 in nontransformed cells leads to cellular transformation, whereas knockout of this gene protects mice from colorectal cancer." (PMID 24675762, 2014). "Studies have also shown that overexpression of DNMT1 in non-transformed cells leads to cellular transformation, whereas knockout of DNMT1 protects mice from colorectal cancer." (PMID 24822169, 2014). "Additionally, we comprehensively characterized the DNA methylation profiles of a colorectal carcinoma cell line pair (HCT116 and DKO, which was generated through double knock-out of DNMT1 and DNMT3b in HCT116)." (PMID 23324053, 2013). "OPCML-v1 could also be induced in the colorectal cancer cell line HCT116 which is completely methylated for this gene, by genetic demethylation through double knock-out of both DNA methyltransferases DNMT1 and DNMT3B (DKO cell line)." (PMID 18714356, 2008). "In this case, we treated the engineered HCT116 human colorectal carcinoma cells with dox for 2 weeks (to generate hypomethylated genomes), terminated the dox treatment and then monitored DNA methylation recovery for 2 weeks as UHRF1 or DNMT1 expression was restored." (PMID 39607687, 2024). "To do this, we initially used the well-characterised pair of colorectal cancer cell lines HCT116 wild type (WT) and double knockout (DKO), which have high methylation levels at most loci in WT and low levels in the daughter cell line DKO due to decreased levels of DNMT1 and DNMT3B enzymes." (PMID 35578268, 2022).
colorectal cancer (continued). "Consistent with this, in HCT116 colorectal cancer cells lacking DNA methyltransferases DNMT1 or DNMT3B, LCT13 expression decreases, while cells lacking both DNMTs or treated with the DNMT inhibitor 5-azacytidine (5-aza) show no change in LCT13 expression." (PMID 28300471, 2017). "We also found that SOX10 could be activated in the colorectal cancer cell line HCT116 which is completely methylated for this gene, by genetic demethylation through only double knockout (KO) of both DNMT1 and DNMT3B (DKO cell line), but not single KO of DNMT1 or DNMT3B alone (1KO or 3BKO cell line)." (PMID 25301735, 2014).
ovarian carcinoma (123 papers, 2008 to 2025). A malignant neoplasm originating from the surface ovarian epithelium. "In ovarian cancer, RRGs like DNMT1 and METTL3 are implicated in resistance to cisplatin and paclitaxel, while m1A regulators such as TRMT10C influence tumor proliferation." (PMID 41029427, 2025). "The findings revealed that the DNMT1 rs2228611 polymorphism is associated with an increased risk of ovarian cancer in Polish women (OR 1.836 (1.143–2.949), p = 0.0114, pcorr = 0.0342)." (PMID 39597087, 2024). "Preclinical models evaluated the association between immunotherapy and the combination of DNMT1 with an enhancer of zeste homologue 2 (EZH2) inhibition in ovarian cancer cells." (PMID 36984544, 2023). "Loss of DNMT1 promoted metastasis in melanoma, hepatocellular carcinoma, prostate cancer and ovarian cancer." (PMID 35418185, 2022). "The Kaplan-Meier survival analysis showed that low expression of DNMT1 was associated with short overall survival (OS) in ovarian cancer patients." (PMID 35418185, 2022). "Ovarian cancer is associated with elevated expression of DNMTs and HDACs and high-level expression of DNMT1 and HDAC1 is prominent in high-grade ovarian tumors." (PMID 24475290, 2014). "In our study we found that the DNMT1 rs2228611 and rs759920 SNPs can be risk factors of ovarian cancer in a Polish population." (PMID 23666104, 2013). "The minor allele of rs9305012 at intron 23 of the DNMT1 gene was found to be associated with a decreased risk for ovarian cancer among Caucasian multivitamin supplement users." (PMID 23049933, 2012). "This study aimed to determine aberrant expression of DNMT1, DNMT3a, and DNMT3b in benign and malignant ovarian tumor tissues for their association with clinicopathological significance and prognostic value." (PMID 22768205, 2012). "In ovarian cancer cell lines, knock-down of DNMT1 and DNMT3b, resulting in loss of CpG hypermethylation, has a negative effect on growth." (PMID 21943380, 2011). "However, only the loss of DNMT1 or DNMT3B significantly restored the ALDH1A2 expression in ovarian cancer cell lines." (PMID 31615043, 2019). "Moreover, DNMT1 is associated with TGF beta-induced EMT in ovarian cancer cells, and SGI treatment prevents this EMT process." (PMID 30547810, 2018). "Therefore, we observed, in a recessive inheritance model, that DNMT1 rs2228611 and rs759920 SNPs are associated with increased risk of ovarian cancer development [OR 1.836 (1.143–2.949), p = 0.0114, and OR 1.932 (1.185–3.152), p = 0.0078, respectively]." (PMID 23666104, 2013). "Our study may suggest that Polish women bearing either the DNMT1 rs2228611 or rs759920 SNP may have an increased risk of ovarian cancer." (PMID 23666104, 2013). "Our results may suggest that DNMT1 variants may be risk factors of ovarian cancer." (PMID 23666104, 2013). "Moreover, we observed, in the recessive inheritance model, that the DNMT1 rs2228611 and rs759920 SNPs are associated with an increased risk of ovarian cancer development [OR 1.836 (1.143–2.949), p = 0.0114, pcorr = 0.0342, and OR 1.932 (1.185–3.152), p = 0.0078, pcor=0.0234, respectively]." (PMID 23666104, 2013). "For example, in ovarian cancer, a feedback loop between miR-30a/c-5p and DNMT1 has been identified as a key regulator of cisplatin resistance and EMT, processes intimately linked to DNA damage repair signaling." (PMID 40805201, 2025). "Further evidence of synergy comes from studies combining azacitidine with Nexturastat A, an HDAC6i, which revealed additive reductions in PD-L1 and DNMT1 expression across multiple ovarian cancer cell lines." (PMID 41029427, 2025). "Increased expression of DNMT1 has been observed in ovarian cancer tumors and their corresponding cell lines, with DNMT1 transcripts being particularly abundant in exosomes isolated from conditioned medium of ovarian cells." (PMID 40757000, 2025).